FZD2 (frizzled class receptor 2)
Diseases named in the same sentence as FZD2 in open-access papers (continued):
Sharing a sentence is not in itself a finding about the gene and the disease.
cancer (37 papers, 2012 to 2025). A tumor composed of atypical neoplastic, often pleomorphic cells that invade other tissues. "Elevated FZD2 expression was associated with poor overall survival (OS) in cancers such as KIRC, LGG, MESO, SARC, and THCA." (PMID 40444048, 2025). "The diagnostic potential of FZD2 across various cancer types was evaluated using ROC curve analysis, with the area under the curve (AUC) calculated to determine its predictive power." (PMID 40444048, 2025). "This study investigates the correlation between FZD2 expression and clinical outcomes, as well as its underlying molecular mechanisms in pan-cancer." (PMID 40444048, 2025). "Further, gene set enrichment analysis revealed that FZD2 is associated with critical pathways such as Notch signaling and oxidative phosphorylation, both of which are essential for cancer cell survival and proliferation." (PMID 40444048, 2025). "A study performing a comprehensive analysis of FZD2 in 33 cancer types indicated that FZD2 was associated with high oncogenicity." (PMID 34986855, 2022). "Wnt5a, Wnt5b, and Fzd2 13 are crucial proteins reported to associate with cancer stemness and mobility." (PMID 27139420, 2016). "FZD2 mRNA expression was correlated with these factors across 33 cancer types to assess how gene mutations might influence FZD2 expression." (PMID 40444048, 2025). "These ROC analyses support FZD2 as a robust diagnostic indicator in these cancers." (PMID 40444048, 2025). "Additionally, we analyzed the association between FZD2 expression and the abundance of 22 types of infiltrating immune cells across pan-cancer." (PMID 40444048, 2025). "FZD2 expression was also associated with N stage in four cancers: KIPAN, HNSC, KIRC, and THCA." (PMID 40444048, 2025). "COSMIC, cBioPortal, and CCLE were used to examine FZD2 mutations in human cancers." (PMID 33565732, 2021). "Our study underscores the critical role of FZD2 in cancer biology, highlighting its potential as both a prognostic biomarker and a therapeutic target, while also laying the groundwork for precision oncology approaches that target its multifaceted functions." (PMID 40444048, 2025). "Our protein-protein interaction (PPI) and co-expression analyses corroborate these findings, demonstrating FZD2’s interaction with proteins involved in Wnt signaling and sphingolipid metabolism, which underscores its multifaceted role in cancer biology." (PMID 40444048, 2025). "Based on the median expression level, patients in these cancers were categorized into high and low FZD2 expression groups." (PMID 40444048, 2025). "Analysis of TCGA data revealed a strong positive correlation between FZD2 expression and advanced cancer stages." (PMID 40444048, 2025). "Frizzled class receptor 2 (FZD2), is a critical protein in the Wnt signaling pathway, which plays significant roles in various cancers." (PMID 40444048, 2025). "Pan-cancer analysis of TCGA and GTEx cohorts showed elevated FZD2 mRNA expression across multiple cancer types." (PMID 40444048, 2025). "Future investigations should focus on elucidating the specific molecular mechanisms by which FZD2 contributes to cancer progression and exploring its application in targeted therapies." (PMID 40444048, 2025). "The findings from our functional assays further support the importance of FZD2 in cancer biology, paving the way for more effective treatment strategies and improved patient outcomes in the future." (PMID 40444048, 2025). "Our study represents the first systematic pan-cancer analysis of FZD2, revealing its dual roles as a prognostic biomarker and molecular driver across 33 cancer types." (PMID 40444048, 2025). "Some reports have demonstrated that the expression of FZD2 varies with the different clinical stages and histological grades in cancers." (PMID 34986855, 2022). "It was implicated to participate in cancer cell growth, migration and invasion and dominantly affected treatment and prognosis, suggesting the importance of FZD2 in cancer." (PMID 34986855, 2022).
cancer (continued). "The mRNA expression profiles related to FZD2 and 7 showed their overexpression in late stages of primary liver and lung cancers compared with normal tissue and early-stage cancer." (PMID 34679012, 2021). "This study also found that FZD2 increases cancer cell motility, migration, and invasion by increasing mesenchymal proteins and MMP-2, MMP-9, and MMP-13." (PMID 34604862, 2021). "We examined FZD2 expression using pan-cancer data of 33 cancer types from The Cancer Genome Atlas (TCGA)." (PMID 33565732, 2021). "Frizzled class receptor 2 (FZD2) belongs to Frizzled family, which has been proven to promote cell growth and invasion in various human cancers." (PMID 33832493, 2021). "The results confirm the importance of FZD2 expression in cancer prognosis and treatment, and provide new clues for treatment strategies." (PMID 33565732, 2021). "Here, FZD2, which induced STAT3 activation, induced the migration and invasion of ESCC cancer cells, and a high level of FZD2 expression predicted a poor prognosis for patients with ESCC." (PMID 32766155, 2020). "A previous study reported that STAT3 interacts with FZD2 and plays a critical role in WNT5a/FZD2-mediated cancer cell metastasis." (PMID 32766155, 2020). "As expected, Cav1 were down‐regulated in most cancer cell lines, accompanied by the enhancement of Fzd2." (PMID 29502342, 2018). "Functional studies will be required to determine if Fzd2 mediates Wnt5a-driven invasiveness in these cancer types." (PMID 22384081, 2012). "M2 macrophages showed the strongest correlation with FZD2 expression in the pan-cancer analysis." (PMID 40444048, 2025). "Notably, significant differences in FZD2 expression were observed across T stages in eight cancers, including STES, KIPAN, STAD, PRAD, KIRC, LIHC, THCA, and KICH." (PMID 40444048, 2025). "Our transdisciplinary approach not only establishes FZD2 as a tissue-specific pan-cancer biomarker with dual utilities (prognostic and therapeutic) but also demonstrates how integrated multi-omics strategies can uncover actionable targets for precision oncology." (PMID 40444048, 2025). "We report that FZD2 is highly expressed in most tumors, differing between cancer types." (PMID 33565732, 2021). "An immunotoxin-based therapeutic strategy against the overexpressed FZD receptors in HCC such as FZD2 and 7 could be a translatable approach to overcome cancer." (PMID 34679012, 2021). "The mutation of W7.55 to L in FZD2, FZD6 and SMO is associated with different forms of cancer." (PMID 30737406, 2019). "In many types of cancer, FZD2 expression was strongly correlated with poor prognosis." (PMID 28500050, 2017). "In many types of cancer, FZD2 expression is strongly correlated with poor prognosis." (PMID 26132195, 2015). "Therefore, this novel mechanism for the regulation of FZD2 expression via miR-203 could be utilized for epigenetic therapy for cancer stem cells." (PMID 26132195, 2015). "Frizzled 2 (FZD2) is an important receptor in the Wnt pathway, with high expression in malignant tumors, and it is related to prognosis." (PMID 40804837, 2025). "Members in FZD family including FZD2, FZD4, FZD7, FZD8 and FZD10 have been demonstrated to mediate cancer cell epithelial-mesenchymal transition (EMT)." (PMID 33618713, 2021). "Recently, a new NCWP involving Wnt5a and the receptor Frizzled2 (Fzd2) was discovered and shown to promote tumor progression and EMT in several cancer cell lines and a mouse xenograft model." (PMID 28030815, 2017). "For example, SFRP4, WNT11, FZD2, MYC were highly expressed in cancer tissues which represent the Wnt pathway was activiated and BCL2A1, ICM1, TNFSF14 in NF-κB pathway were highly expressed as well." (PMID 25928635, 2015). "Specifically, FZD2 has been recognized as a critical receptor in the non-canonical Wnt pathway and is highly expressed across various cancers, where it serves as a marker of poor prognosis." (PMID 40444048, 2025).
cancer (continued). "Unlike single-cancer studies, we uncovered FZD2’s context-dependent functions in both canonical Wnt activation (e.g., Wnt3A/ROR2 axis) and immune evasion mechanisms (e.g., M2 macrophage recruitment)." (PMID 40444048, 2025). "After analysis, FZD2 overexpression was identified to be correlated with worse distant metastasis free survival (DMFS), indicating the potential involvement of FZD2 in cancer progression." (PMID 33832493, 2021). "Previous studies have shown that FZD2 promotes cancer development by activating both the canonical and non-canonical WNT pathways." (PMID 32766155, 2020). "FZD2 is one of the most important receptors in non-canonical Wnt pathways and FZD2 expression is strongly correlated with poor prognosis in several types of cancer." (PMID 27323822, 2016). "Sequencing results showed that Wnt7a, Wnt7b, Fzd2, Mmp7 and Ccnd2 in the Wnt signaling pathway were downregulated after PRDX6 knockout, suggesting that this signaling pathway may be involved in the regulation of PRDX6's cancer-promoting effect." (PMID 36209344, 2022). "However, one study showed that FZD2 inhibited the cell growth and migration in salivary adenoid cystic carcinomas (SACC), indicating that FZD2 may exert different functions in various cancers." (PMID 29789460, 2018). "Frizzled2 (FZD2) is a receptor for Wnts and may activate both canonical and non-canonical Wnt signaling pathways in cancer." (PMID 27323822, 2016). "Through non-canonical signaling, FZD2 induces EMT, promotes migration, increases cell motility, and stimulates tumorigenesis in various cancers, highlighting its potential to be a target for chemoprevention." (PMID 34604862, 2021). "Of note, four of the cancer genes present in the network (MAP2K2, E2F1, FZD2, and WNT7B), although absent from our high-confident list of CIRBP targets, are enriched in CIRBP IPs." (PMID 33172965, 2021).
infection (3 papers, 2019 to 2021). The state of being infected such as from the introduction of a foreign agent such as serum, vaccine, antigenic substance or organism. "Colocalization of E. chaffeensis with Fzd2, 4, 5, 7, and 9 suggested these proteins serve as receptors for infection." (PMID 33883266, 2021).
CNS tumor (1 paper, 2023). "In keeping herewith, we show through ChIP-seq data that components of the Wnt-pathway such as FZD2 and FZD9 are direct targets of PLAGL1 and PLAGL2 and are overexpressed in the PLAGL1/2-amplified samples compared to the other CNS tumor types." (PMID 36437415, 2023).
skeletal dysplasia (1 paper, 2019). Any Mendelian diseases that affects growth and development of the skeleton. "Interestingly, while nonsense variants in FZD2 cause severe skeletal dysplasia phenotypes, we identified missense variants in this gene in individuals with ISS, suggesting that missense variants are associated with a milder phenotype." (PMID 30809043, 2019).
FZD2 also shares sentences with these, for which no sentence is quoted: colon cancer (3 papers); cleft palate (2); glioblastoma (2); pancreatic cancer (2); acute lymphoblastic leukemia (1); cervical squamous cell carcinoma (1); cholangiocarcinoma (1); chronic obstructive pulmonary disease (1); cleft lip (1); colon adenocarcinoma (1); colonic adenoma (1); craniorachischisis (1); embryonal carcinoma (1); esophageal adenocarcinoma (1); esophageal squamous cell carcinoma (1); head and neck cancer (1); heart defects (1); kidney cancer (1); meningioma (1); mesenchymal tumor (1); osteosarcoma (1); ovarian serous cystadenocarcinoma (1); pancreatic adenocarcinoma (1); pheochromocytoma and paraganglioma (1); psoriasis (1); rectal adenocarcinoma (1); renal carcinoma (1); rheumatoid arthritis (1); serous carcinoma (1); skin cutaneous melanoma (1).
A further 4 diseases each share a sentence with FZD2 in 1 paper.